CRP (C-reactive protein)
Diseases named in the same sentence as CRP in open-access papers (continued):
Sharing a sentence is not in itself a finding about the gene and the disease.
bacteremia (continued). "Neutrophil-lymphocyte count ratio (NLCR) has been reported as better indicator of bacteremia than procalcitonin (PCT), and more precise predictor of mortality than C-reactive protein (CRP) under various medical conditions." (PMID 33622247, 2021). "Independent factors derived from the primary cohort to predict MDRO colonization or infection were male sex, higher C-reactive protein (CRP) levels and higher Pitt bacteremia scores (Pitt scores), which were all assembled in the nomogram." (PMID 32430043, 2020). "At the onset of the bacteremia, patients receiving TPN showed a significantly lower level of C-reactive protein with a mean of 74.6 mg/L versus 169 mg/L (p < 0.001)." (PMID 33066383, 2020). "Previous studies have compared the use of procalcitonin and C-reactive protein (CRP) with traditional laboratory tests, such as WBC, in predicting serious bacterial infections, including bacteremia." (PMID 32435627, 2020). "Well-known inflammatory markers, such as CRP and procalcitonin (PCT), have been studied to predict bacteremia because they can be rapidly evaluated compared to confirming positive blood cultures, which is time-consuming." (PMID 32161316, 2020). "The secondary object of this study was to determine the usefulness of procalcitonin, C-reactive protein (CRP), qSOFA score and lactate in predicting bacteremia and 28-day mortality." (PMID 31212806, 2019). "For bacteremia, AUROC of CRP, lactate, serum PCT, and whole blood PCT were 0.619 (95% CI, 0.523–0.715), 0.748 (95% CI, 0.669–0.826), 0.736 (95% CI, 0.646–0.826) and 0.736 (95% CI, 0.642–0.833), respectively." (PMID 31212806, 2019). "Currently available routine screening for bacterial sepsis include the white blood cell (WBC) count, erythrocyte sedimentation rate (ESR), and C-reactive protein (CRP), although these have poor sensitivity and specificity." (PMID 29495352, 2018). "NLCR, CRP, procalcitonin, neopterin and pro-ADM levels were insignificant in diagnosis of bacteremia in critically ill patients." (PMID 30559815, 2018). "As a result, NLCR, CRP, procalcitonin, neopterin and pro-ADM levels were insignificant in diagnosis of bacteremia." (PMID 30559815, 2018). "The present study found that MPV had a superior discriminative value to that of CRP (AUC: 0.629 and, 0.606 respectively) and MPV performed a better performance than CRP in differentiating true bacterial sepsis (47.6% and 42.1%, respectively)." (PMID 30190753, 2018). "For diagnosing bacterial sepsis, the NLCR showed a significantly higher AUC (0.68; 95% CI 0.65–0.71) than PCT (p = 0.019; AUC 0.64; 95% CI 0.61–0.67), CRP (p < 0.001; AUC 0.57; 95% CI 0.54–0.60), and lactate (p < 0.001; AUC 0.57; 95% CI 0.54–0.60)." (PMID 28727802, 2017). "Both CRP and PCT are today routinely employed in clinical practice but have limited abilities to distinguish bacterial sepsis from other inflammatory conditions." (PMID 28727802, 2017). "Even after excluding episodes of AGPN with bacteremia, the AUC of DNI values was also larger than that of WBC counts and CRP concentration." (PMID 26275220, 2015). "Diagnostic performances of ProADM seem excellent, especially to rule-out bacteremia (sensitivity 100 %), and as accurate as classical markers (WBC, Band neutrophils, and CRP) with regards to specificity." (PMID 26286191, 2015). "The CRP, MELD, bacteremia, and SIRS levels were all elevated in the high-DNI group, but the differences were not statistically significant." (PMID 24466280, 2014). "In a retrospective study, the NLCR proved to be a simple and even better marker in predicting bacteremia than routine parameters, like white blood cell (WBC) count and C-reactive protein (CRP) level, in infectious emergency admissions." (PMID 23049706, 2012). "In both groups (patients with GPB vs. GNB) peak concentrations of CRP and WCC levels were observed one day following onset of bacteremia (P = 0.009, and P = 0.008), respectively." (PMID 17868441, 2007).
bacteremia (continued). "CRP and WCC count measurements were recorded daily from two days prior (d-2) until one day after onset of bacteremia (d+1)." (PMID 17868441, 2007). "Patients with GPB demonstrated lower CRP and WCC levels at onset of bacteremia, which remained almost stable during the four study days." (PMID 17868441, 2007). "To evaluate whether combining MDW with other biomarkers could improve bacteremia prediction, we constructed three two-biomarker models: MDW + NLR, MDW + WBC and MDW + CRP." (PMID 41598332, 2026). "The bacteremia in mice treated with either WT CRP (group D) or E-CRP-1 (group E) was not significantly different from bacteremia in untreated mice (group A)." (PMID 40740789, 2025). "Similarly, inflammatory markers (CRP, PCT, WBC, and neutrophil granulocyte count) showed markedly higher values in the bacterial sepsis group." (PMID 40722789, 2025). "Similarly, the presence of qSOFA score ≥2, SIRS, and CRP > 10 mg/dL had a + LR of 2.06 (95% CI, 1.07–3.06), –LR of 0.34 (95% CI, 0.12–0.94), and NPV of 91.1% (95% CI, 88.7–93.5) for predicting bacteremia." (PMID 40627656, 2025). "IL-6 showed no discriminative power for bacteremia and correlated weakly with CRP only on Days 1–2 (r = 0.25, p = 0.02)." (PMID 40647525, 2025). "Bacteremia was not reduced in mice treated with WT CRP 12 h after inoculation, except at 36 h time point." (PMID 40740789, 2025). "Despite IL-6’s superior sensitivity compared to CRP (74% vs. 29%), its elevation in 57% of FUO episodes and failure to detect 26% of bacteremia precluded standalone use for antibiotic decisions, underscoring the limitations of single biomarkers in neutropenic fever management." (PMID 40647525, 2025). "Non-bacteremic infections showed intermediate levels, while bacteremia (especially Gram-negative under antibiotic treatment) had the highest CRP peaks." (PMID 39467995, 2024). "(2016) analyzed 3023 samples (2819 fever case samples and 204 control samples) and found that the positivity rates of interleukin-6 (IL-6) and IL-10 in children with bacteremia were 92.8% and 82.2%, respectively, which were higher than those of PCT (33.8%) and CRP (73.1%)." (PMID 39559703, 2024). "Patients who were treated with ciprofloxacin versus non-ciprofloxacin regimens had lower CRP levels and lower Pitt bacteremia scores (1.5 ± 2.3 versus 2.2 ± 2.5, p = 0.04)." (PMID 39200009, 2024). "In laboratory examinations, the percentage of neutrophils and CRP levels were significantly higher in the bacteremia group than in the non-bacteremia group (both P < 0.05)." (PMID 37679686, 2023). "In laboratory examinations, higher neutrophil counts were found in infants with bacteremia in all three age groups, but higher CRP levels were only noted in age groups 1 and 2 (both P < 0.05)." (PMID 37679686, 2023). "Based on the ROC analysis results, we established significant cutoff values for neutrophil counts and CRP concentration to discriminate the presence or absence of bacteremia in this population." (PMID 37679686, 2023). "Therefore, in order to anticipate bacteremia detection prior to blood culture end-result, laboratory biomarkers such as Complete Blood Count (CBC), procalcitonin, and C-Reactive Protein (CRP) have been adopted into clinical practice." (PMID 36502550, 2023). "Within the bacteremia group, there is a notably stronger and more pronounced negative correlation between CRP levels and the Z score of Hb (r = −0.41, p < 0.001), in contrast to the non-bacteremia group (r = −0.115, p < 0.049)." (PMID 37628401, 2023). "Despite CRP being the only biomarker present in FN guidelines, its values do not help discriminate between the bacteremia group and the group without bacteremia." (PMID 37081067, 2023). "In patients with bacteremia, IL-6 was the first to increase, followed by PCT and CRP." (PMID 36555941, 2022).
bacteremia (continued). "Presepsin (OR 2.28, 95% CI 1.41–3.70; p < 0.001) and PCT (OR 5.18, 95% CI 3.13–8.56; p < 0.001) were found to be the independent predictors of bacteremia, but CRP was not." (PMID 36072944, 2022). "In conclusion, the present findings showed that procalcitonin, rather than presepsin and CRP, was a modestly useful marker for non-severe bacteremia, and that tachypnea (≥ 22/min) itself, rather than the qSOFA score, can be used as a key bacteremia predictor." (PMID 35778478, 2022). "It was also related to lactate, but not to procalcitonin or C reactive protein, nor was it related to bacteremia." (PMID 35048314, 2022). "The discrepancy from our study suggests that measuring IL-6 with CRP and/or PCT may be useful to detect infection or bacteremia more quickly and correctly in diverse situations." (PMID 36555941, 2022). "As expected, PCT and CRP/PCT values were significantly different in patients with bacteremia compared to those with negative blood cultures." (PMID 33777975, 2021). "In this large prospective multicenter study of children with CAP, we investigated whether routinely available biomarkers such as WBC, ANC, CRP, and PCT were able to predict bacteremia." (PMID 34746044, 2021). "In this comparative study, we present the distribution of FCBI-index, CRP and PCT values primarily in bacteremia, microbiologically confirmed local bacterial infection, clinically diagnosed probable bacterial infection, and microbiologically confirmed viral respiratory tract infection (RTI)." (PMID 34844193, 2021). "The animals that received only the Fh15 infusion did not develop bacteremia, endotoxemia, CRP, or PCT at any time throughout the study (data not shown)." (PMID 34937173, 2021). "The mean values of PCT, PSPN, and CRP were reported on the first day of the patients’ group with and without bacterial sepsis." (PMID 34324506, 2021). "Our study showed that the diagnostic performance of the IMS was similar to CRP and better than PCT to detect bacteremia in patients with and without malaria co-infection." (PMID 33647009, 2021). "Hence, we aimed to investigate the value of CRP and PCT to determine the value of each marker for early detection of true bacteremia for better management of these patients." (PMID 33178372, 2020). "Age, percentage of neutrophil and band, ANC, Hb, platelet, and CRP were statistically different between bacteremia and non-bacteremia encounters." (PMID 32429293, 2020). "Overall, the results of blood routine (neutrophil, lymphocyte, and monocyte counts) and infection biomarkers (C-reactive protein, ferritin, and procalcitonin levels) in SARS-CoV-2 sepsis patients and bacterial sepsis patients showed the same upward and downward trend relative to normal ranges." (PMID 33329592, 2020). "Combined data from survival of mice and bacteremia suggested that H38R CRP was not protective against pneumococcal infection and that the lethality of H38R CRP-treated mice was due to the inability of H38R CRP to decrease bacteremia." (PMID 32903624, 2020). "IL-8 levels decreased within 72 h and considerably earlier than CRP when there has been no documented bacteremia or recent remote site infection." (PMID 32076032, 2020). "Only PCT and combination of PCT and CRP were statistically significant in distinguishing bacteremia from nonbacteremia patients." (PMID 33178372, 2020). "The area under the curve for differentiating bacteremia from nonbacteremia for PCT (0.741) was superior to that of CRP (0.612)." (PMID 33178372, 2020). "Infected mice injected with H38R CRP showed no reduction in bacteremia and did not survive longer, as opposed to infected mice treated with wild-type CRP." (PMID 32903624, 2020). "Consistent with the survival data, the combination of WT CRP and clarithromycin (group D) did not significantly affect the protective ability of clarithromycin in terms of decreasing bacteremia." (PMID 33552084, 2020).
bacteremia (continued). "IL-8 relatively decreased from 72 h and the decreased was considerably earlier than in CRP in the absence of documented bacteremia or recent remote site infection." (PMID 32076032, 2020). "In fixed specificities, the sensitivities of PCT were higher than CRP in bacteremia versus nonbacteremia groups." (PMID 33178372, 2020). "In another study in which adult patients were evaluated after admission to the emergency department with suspected community-acquired bacteremia, both lymphocytopenia and the NLR were found to be better predictors of bacteremia than WBC and neutrophil counts and CRP." (PMID 31428594, 2019). "Although bacteremia (+) patients had higher CRP levels than bacteremia (-) patients, CRP levels were not significantly different among the four groups (P > 0.05)." (PMID 31821331, 2019). "In 289 febrile episodes from non-HSCT patients, PCT and CRP levels were higher in 34 bacteremia cases than those in 255 non-bacteremia cases (PCT: 0.91 (0.27–5.51) ng/mL vs. 0.22 (0.18–0.28) ng/mL, P < 0.001; CRP: 125.7 (91.3–159.8) mg/L vs. 67.4 (55.7–81.9) mg/L, P = 0.002)." (PMID 31821331, 2019). "In this single-center observational study, PCT was more valuable than CRP for discriminating between bacteremia and non-bacteremia independent of neutropenia or HSCT." (PMID 31821331, 2019). "In 341 non-neutropenic febrile episodes, both PCT and CRP levels discriminated bacteremia from non-bacteremia (PCT: 0.97 (0.27–5.61) ng/mL vs. 0.20 (0.17–0.24) ng/mL, P < 0.001; CRP: 146.1 (78.9–240.2) mg/L vs. 52.2 (46.4–62.0) mg/L, P < 0.001)." (PMID 31821331, 2019). "In summary, for febrile episodes from patients with hematologic malignancy, PCT was more valuable than CRP for discriminating between bacteremia and non-bacteremia independent of neutropenia." (PMID 31821331, 2019). "For non-neutropenic febrile episodes, both PCT and CRP discriminated bacteremia from non-bacteremia." (PMID 31821331, 2019). "There was also no significant influence of the CRP value on the appearance of a catheter-related bacteremia." (PMID 31151433, 2019). "When comparing the AUC in severe bacterial sepsis/septic shock for the biomarkers, lactate had the highest AUC (0.81; 95% CI 0.77–0.85) among the single biomarkers and was significantly better than PCT (p = 0.01), the NLCR (p < 0.01) and CRP (p < 0.001)." (PMID 28727802, 2017). "APACHEII score, peripheral blood leukocyte count, and C-reactive protein level were higher in the CSKp group than in the CRKp group at the time of bacteremia, albeit not significantly so." (PMID 29026535, 2017). "In our study, we found that IL-8 was a strong predictive marker for bacteremia, particularly for gram-negative bacteremia, as compared to IL-6 and CRP." (PMID 28148470, 2017). "Bacterial infection was excluded from our study and these findings do not apply to cases of superimposing bacterial sepsis in patients with dengue with high CRP levels." (PMID 26247033, 2015). "Endocan levels at day 0 in patients with bacteremia were higher than those without bacteremia (1.09 ng/mL vs 0.82 ng/mL, P=0.002), but neither CRP levels nor PCT levels at day 0 were different between the two groups." (PMID 25894539, 2015). "Of case infants without evidence of bacteremia on PCR or BC, 5.0% (9/181) had a raised CRP on day one, rising to 16.2% (19/117) on day 3 amongst survivors." (PMID 24836781, 2014). "Although CRP changes in fever seemed to be interesting to determine new onset infection, CRP concentration was significantly lower in patients with bacteremia than in those without (9.6 ± 6.5 versus 13.2 ± 8 mg/dL, P = 0.03)." (PMID 24286072, 2013). "The disease severity according to the grading scale did not correlate with the proportion of patients with bacteremia, or with the peak plasma C-reactive protein during the admission." (PMID 24069468, 2013). "On the contrary, CRP levels have no value for diagnosis of patients with bacteremia and a high fever in the emergency department." (PMID 22809118, 2012).
bacteremia (continued). "Using 50 mg/l as the cut-off point, the positive predictive value (PPV) of CRP in diagnosing bacteremia was 54.3% against a negative predictive value (NPV) of 59.6%." (PMID 21034463, 2010). "Our observations clearly show that lymphocytopenia performs better in predicting bacteremia in an emergency care setting than either the WBC count, neutrophil count or CRP level, with the PPVs and NPVs of lymphocytopenia outweighing predictive values of standard laboratory parameters." (PMID 21034463, 2010). "In a follow-up study, Wyllie and colleagues showed that CRP alone performed no better in bacteremia prediction than either a model combining lymphocytopenia and neutrophilia, or lymphocytopenia alone." (PMID 21034463, 2010). "This was confirmed in our linear mixed model, which showed citrulline but not bacteremia related to the CRP response." (PMID 21188146, 2010). "The present study only investigated the dynamics of two variables (CRP and WCC) in their ability to differentiate between bacteremia caused by Gram positive vs. Gram negative pathogens." (PMID 17868441, 2007). "Although our cohort already had high baseline CRP and WCC count serum concentrations, some differential observation could be made after the onset of bacteremia with respect to both biomarkers." (PMID 17868441, 2007). "C-reactive protein (CRP) levels rise 10-12 hours post-infection, suggesting that early testing may not be optimal for predicting bacteremia." (PMID 40809608, 2025). "Additionally, with a negative predictive value of 92%, CRP at a cut-off of 10 mg/l demonstrated high effectiveness in ruling out bacterial sepsis." (PMID 40598497, 2025). "However, the suspicion of bacteremia relies on the combined interpretation of routine laboratory tests, such as complete blood count (CBC), differential count (DC), and elevated C-reactive protein (CRP)." (PMID 41695261, 2025). "However, when the presence of bacteremia, regardless of the bacterial species isolated, was incorporated as an additional criterion, the CRP + PCT combination achieved an improved performance, with 90% sensitivity, 80% specificity, and an AUC of 0.88." (PMID 41011807, 2025). "The limited immunological response suggested at the gene expression level in young infants with UTI without bacteremia was unexpected due to the indications of systemic inflammation, such as elevated C-reactive protein, white blood cell count, and absolute neutrophilic count, within this group." (PMID 38732074, 2024). "Notably, there was a more significant negative correlation with CRP levels and Z scores of Hb in the bacteremia group (r = −0.41, p < 0.001) than in the non-bacteremia group (r = −0.115, p < 0.049)." (PMID 37628401, 2023). "Moreover, infants with bacteremia, particularly those aged less than 60 days, had significantly higher CRP levels than those without bacteremia." (PMID 37679686, 2023). "Furthermore, the bacteremia group exhibited a more substantial negative correlation between CRP levels and a Z score of Hb (r = −0.41, p < 0.001) compared to the non-bacteremia group (r = −0.115, p < 0.049)." (PMID 37628401, 2023). "There was no significant change in CRP or prevalence of bacteremia." (PMID 34297188, 2022). "Additionally, the results of our study and several other studies have indicated that patients with bacteremia tend to have a higher white cell count and CRP level than those without bacteremia." (PMID 35887987, 2022). "This correlation in non-existent for CRP, leukocytes or Pitt bacteremia score." (PMID 35443013, 2022). "Therefore, the predictive model trained with only CBC/DC data can be inferred to have provided a similar level of prediction capability on the occurrence of bacteremia without using any CRP and PCT test results as predictors." (PMID 35351003, 2022).